INS (insulin)
Diseases named in the same sentence as INS in open-access papers (continued):
Sharing a sentence is not in itself a finding about the gene and the disease.
Insulin resistance (continued). "Insulin sensitizers such as metformin decreases insulin resistance by altering the PI3K/AKT/mTOR pathway." (PMID 34225729, 2021). "We found that inhibiting Drp1 attenuates the impairment in skeletal muscle insulin signaling and improves whole‐body glucose tolerance in the setting of obesity‐induced insulin resistance." (PMID 33904649, 2021). "Failure of insulin secretion to overcome insulin resistance is regarded by many as the key event leading to type 2 diabetes." (PMID 34206745, 2021). "Insulin resistance is a pathological condition in which cells fail to respond to normal circulating insulin levels, so insulin cannot provide average glucose and lipid homeostasis." (PMID 34311759, 2021). "Animal exposure studies focusing on audible noise with higher frequencies found an increase in insulin resistance, fasting hyperglycemia, dyslipidemia, and alterations in insulin signaling in the skeletal muscle." (PMID 34446814, 2021). "HOMA-IR is often considered a measure of hepatic insulin resistance, while Matsuda represents a whole-body measure of insulin sensitivity and depends on not only hepatic but also skeletal glucose disposition." (PMID 33854039, 2021). "The ability to induce insulin resistance is associated with activation of SOCS3, an inhibitor of insulin signaling in adipocytes." (PMID 33810619, 2021). "Our previous studies show that SIT controls hyperglycemia and insulin resistance by promoting insulin signaling via activation of insulin receptor and glucose transporter 4 (GLUT 4) proteins in adipose tissues of obesity induced type-2 diabetic rats." (PMID 33917607, 2021). "The intake of caffeine is reported to promote insulin resistance, whilst a consumption of decaffeinated coffee is shown to improve insulin sensitivity." (PMID 33917297, 2021). "In such IEI, insulin synthesis is generally maintained, and extremely increased insulin resistance has been suggested to contribute to the development of DM." (PMID 34887872, 2021). "Proinflammatory cytokines and mediators closely correlate with insulin resistance through interfering with insulin signal transduction." (PMID 34284806, 2021). "Obesity brings about disturbances in fecundity not only via an increased oestrogen concentration, but also as a consequence of higher insulin concentration and insulin resistance, which was exposed as an increased HOMA-IR." (PMID 34003845, 2021). "Insulin resistance means that insulin stimuli fail to induce an appropriate biologic response, such as glycemic control." (PMID 34503545, 2021). "Subjects with obesity had higher fasting plasma insulin concentrations, indicating insulin resistance, and higher fasting leptin concentrations." (PMID 34331964, 2021). "Aspirin, a COX inhibitor, suppresses insulin sensitivity in healthy human, but improves insulin resistance in diabetic patients." (PMID 33879780, 2021). "When insulin resistance occurs, the hepatic insulin signaling pathway is inhibited, but liver lipid synthesis increases." (PMID 34658856, 2021). "Both in people and in rats, decreased insulin secretion as well as increased insulin resistance are believed to contribute to the hyperglycemia." (PMID 34680012, 2021). "Insulin treatment was incorporated into the study in order to implement a model for insulin resistance and related hyperinsulinemia, conditions that are often observed in obese and prediabetic patients." (PMID 33690729, 2021). "Hepatic insulin action is required for lipid synthesis, glucose production and the development of hepatic steatosis during insulin resistance." (PMID 34461916, 2021). "Aronia melanocarpa berries and red ginseng have been reported to improve insulin resistance and promote glucose-stimulated insulin secretion." (PMID 34359426, 2021). "Ceramides and related sphingolipids, as mediators of insulin resistance, cell death, and inflammation, can interfere with insulin signaling, suggesting that they play an important role in DMMCI." (PMID 34276557, 2021).
Insulin resistance (continued). "Pro-inflammatory cytokines contribute to insulin resistance in the liver by inhibiting insulin signal transduction." (PMID 33431899, 2021). "Due to high metabolic demand, insulin resistance has a significant impact in skeletal muscles, adipocytes and liver, since skeletal muscle and adipocytes account for 60–70% and 10% of insulin, respectively, for the uptake of glucose via GLUT4." (PMID 33673200, 2021). "Treatment of high-dose of insulin-induced insulin resistance HepG2 cells as demonstrated by a substantial reduction in glucose uptake in the insulin-resistant group." (PMID 33672051, 2021). "Cirrhosis can aggravate insulin resistance and disturb the molecular mechanisms of insulin on hepatocytes." (PMID 34118892, 2021). "When insulin resistance is elevated, insulin secretion must be increased, but if insulin secretion cannot compensate for insulin resistance, T2DM can be induced." (PMID 34068659, 2021). "It has been used as proxy assessment of insulin resistance (IR) and is a good index of the balance between endogenous glucose production and cell insulin secretion, based on the Matthews formula." (PMID 34827338, 2021). "In this regard, in situations of insulin resistance, the downregulation of insulin signaling with reduced activity of mTORC2 derepresses MCP1 and will attract monocytes to adipose tissue, which will be converted into M1 macrophage." (PMID 33648564, 2021). "Four features were the most relevant: insulin resistance, ferritin, serum levels of insulin, and triglycerides." (PMID 34204225, 2021). "Insulin resistance was estimated by fasting blood insulin (FINS), homeostasis model assessment-insulin resistance (HOMA-IR), and body mass index (BMI)." (PMID 34956436, 2021). "Ceramides stimulate insulin resistance in several metabolically active tissues including SM, which is the main site of insulin-stimulated glucose disposal." (PMID 34440852, 2021). "Insulin resistance is determined by impaired sensitivity to insulin in its main target organs: adipose tissue, liver and muscle." (PMID 34943849, 2021). "Previous studies have reported that insulin secretion was lower, and insulin resistance was improved, in the ETRE group compared with the control group." (PMID 34371933, 2021). "The main mechanism by which TNF-α induces insulin resistance is by triggering post-receptor serine phosphorylation of insulin receptor substrate-1 (IRS-1) thereby interfering with the insulin signalling pathway." (PMID 33800490, 2021). "Researchers in the United States conducted a study to identify a correlation between serum insulin levels and insulin resistance on body fat growth in African-American and Caucasian children." (PMID 33924229, 2021). "Insulin resistance is defined as a complex pathological condition of abnormal cellular and metabolic response to insulin." (PMID 33815291, 2021). "Tzanela and colleagues showed that leptin levels are higher at the onset of sepsis and they correlate with insulin levels and insulin resistance." (PMID 33907162, 2021). "Although Type 2 diabetes is often considered to be a condition of insulin resistance, an alternative interpretation of the available data is that it is the high insulin levels themselves (i.e., hyperinsulinaemia) that are the primary issue." (PMID 34336909, 2021). "The median values of insulin and homeostasis model assessment of insulin resistance (HOMA-IR) were higher among Black compared to White participants (p < 0.05)." (PMID 34065158, 2021). "Insulin resistance was characterized by acanthosis nigricans in the neck, axilla, and back, as well as by the very high insulin requirements (15 IU/kg/day) and by the low levels of total serum adiponectin (0.5 mg/L – normal range: 3.6–9.6 mg/L)." (PMID 34342583, 2021).
Insulin resistance (continued). "With regard to mRNA expression of SOCS 1 and SOCS3, almost all insulin-sensitive tissues showed a strong up-regulation in rodent models of insulin resistance, revealing a robust and direct relationship between insulin resistance and SOCS." (PMID 34574169, 2021). "Consistent with the important role of inflammation in obesity-induced insulin resistance, therefore, we verified that insulin response is similar between WT and OE mice under HFD fed." (PMID 34675215, 2021). "Insulin resistance is defined as a decreased effect of the hormone on its targets for a similar concentration of plasma insulin." (PMID 33669443, 2021). "It is important to evaluate the degree of hyperinsulinemia, in part because it increases to compensate for insulin resistance, and because it is related to the primary alteration in insulin liver catabolism." (PMID 34357331, 2021). "In our previous study conducted on the same group of rats, we showed that F10 versus F60 stimulated higher secretion of insulin and C-peptide by the pancreatic islet cells, and lead to more pronounced insulin resistance." (PMID 35008629, 2021). "Simultaneously, when cytokines and free fatty acids were used to induce chronic ROS accumulation and insulin resistance in rat L6 myotubes in vitro, AX enhanced insulin sensitivity and PI3K/Akt activation by insulin." (PMID 35010981, 2021). "Among Ethiopian people with HIV initiating ART, short-term LNS intake increased glucose and insulin levels, and tended to increase HbA1c, potentially leading to more insulin resistance." (PMID 34657634, 2021). "Vitamin D has been reported to inhibit fat accumulation, increase insulin secretion, preserve pancreatic β-cells, decrease insulin resistance and reduce appetite." (PMID 33928108, 2021). "IKK is activated both by TNFα in the case of peripheral insulin resistance and by Aβ in the brain, resulting in decreased neuronal insulin sensitivity." (PMID 34070553, 2021). "On the other hand, muscle insulin resistance has been reported to be induced by different defects, such as impaired insulin signal transduction due to low-grade inflammation and intramyocellular lipid accumulation." (PMID 34702849, 2021). "Researchers at the University of Washington confirmed that MMP12 regulates insulin sensitivity and is positively correlated with insulin resistance." (PMID 34863141, 2021). "In this work, the levels of circulating insulin together with peripheral insulin resistance ensure that our experimental model corresponds to type 2 diabetes." (PMID 34202017, 2021). "This complication can lead to DKA recurrence, likely due to increased insulin resistance from inflammation and pain and from reduced oral intake and insulin administration." (PMID 33747574, 2021). "Conversely, increased IGF-1 levels are paralleled with improvements in insulin sensitivity in premenopausal obese women with insulin resistance consuming a calorie-restricted diet." (PMID 33816541, 2021). "Recently, we demonstrated that during mid-gestation the combined exposure to DHT and INS mimics the in vivo hyperandrogenism and insulin resistance seen in humans and increases mitochondrial abnormalities in the gravid uterus and placenta." (PMID 34180022, 2021). "GDM patients are shown to have insulin resistance combined with impaired secretion of insulin due to a defect in pancreatic β-cell function." (PMID 33021758, 2021). "The main pathophysiological features in patients with T2D are impaired insulin secretion and insulin resistance in liver, skeletal muscle, and adipose tissue." (PMID 34677406, 2021). "Accordingly, cinnamon mitigates insulin resistance and enhances glucose utilization by increasing phosphatidylinositol 3-kinase activity in the insulin signaling pathway, thus potentiating the insulin action." (PMID 34627352, 2021).
Insulin resistance (continued). "Among these, insulin resistance, insulin signaling, FOXO signaling and AMPK signaling were major pathways to be over-represented with more than ten DEGs being involved in each pathway." (PMID 34190986, 2021). "The most common form is T2D, in which two related features converge: insufficient insulin production by pancreatic β-cells and progressive insulin resistance." (PMID 34638914, 2021). "Exercise was found to improve insulin sensitivity in adipose tissue and decrease the flow of fatty acids to the liver, thereby reducing hepatic fat accumulation and insulin resistance." (PMID 36994336, 2021). "Recently, METS-IR, a non-insulin-based insulin resistance, has been reported to have strong predictive abilities for CVD risk." (PMID 34442386, 2021). "By controlling fasting blood glucose, reducing fasting insulin level and improving insulin resistance, tumor necrosis factor (TNF) and IL-6 levels in vivo can be significantly reduced, and inflammatory state in vivo can be significantly improved." (PMID 34531719, 2021). "The pathogenesis of impaired glucose regulation and eventually T2D is largely influenced by insulin resistance, with decreased insulin-stimulated glucose uptake in tissues resulting in elevated BG levels." (PMID 34050828, 2021). "The treatment of diabetes mellitus and insulin resistance also targets tyrosine phosphatase 1β (PTP1β) which blocks insulin-dependent signaling by insulin receptor dephosphorylation." (PMID 33922000, 2021). "Dapagliflozin treatment improved insulin resistance by decreasing glucose and insulin levels, increased serum magnesium levels, and reduced urinary magnesium excretion." (PMID 34836340, 2021). "Exacerbated production of ROS has been reported to disrupt normal insulin response in skeletal muscle, leading to insulin resistance." (PMID 33806797, 2021). "Decreased circulating levels of serum insulin and leptin also supported the improved insulin resistance in Tg mice." (PMID 33856409, 2021). "Few studies investigated the ethnical difference in the relative relationship between post-challenge insulin secretion and insulin resistance." (PMID 34917033, 2021). "The stress response drives insulin resistance at a time when patients are likely to have poor oral calorie intake and omit their insulin or diabetic tablets for fear of hypoglycemia." (PMID 33677649, 2021). "The two dietary regimens proved similarly effective in improving insulin resistance and fasting hyperinsulinemia, while enhancing endogenous insulin clearance and β-cell glucose sensitivity." (PMID 33919503, 2021). "We and others have demonstrated that T2D is an inherited disease characterized by insulin resistance in insulin target tissues, notably adipose tissue, skeletal muscle, liver and pancreatic b-cells." (PMID 33479282, 2021). "In the past decade, studies on insulin resistance have gradually revealed a relation between low-grade systematic inflammation and pathological insulin sensitivity, which was evidenced by changes in biochemical markers of inflammation." (PMID 34745416, 2021). "Insulin resistance is a key feature of T2D, leading to impaired insulin-stimulated glucose uptake and decreased insulin suppression of HGP." (PMID 32897388, 2021). "Insulin resistance occurs when the activity of insulin is blunted in liver, muscle and adipose tissue and is linked to intra-abdominal fat." (PMID 33776816, 2021). "It decreased plasma glucose, accelerated insulin level, and decreased insulin resistance, all of which were better under diabetic conditions." (PMID 33572627, 2021). "In the present study, insulin resistance was only present in a pre-symptomatic phase of the disease, reinforcing the notion that insulin dysregulation enhances the pathophysiology of AD." (PMID 34206322, 2021).
Insulin resistance (continued). "In the present study, the HOMA-β index was significantly higher in the MIT+T group compared to that in the MIT group, which was mainly caused by insulin resistance induced by TCDD, resulting in abnormal insulin secretion." (PMID 34948750, 2021). "In this case, however, insulin action is instead blocked downstream of the IR, as evidenced by 75% reduction in intracellular AKT levels response to insulin, leading to insulin resistance by this alternative mechanism." (PMID 33477364, 2021). "Fasting plasma glucose, 2-hour post 75 g glucose load plasma glucose (2-hPLG), fasting serum insulin, homeostasis model assess- ment of insulin resistance (HOMA-IR), HbA1C, and serum 25OHD at 6 - 12 weeks after delivery." (PMID 34670305, 2021). "This alteration of insulin signal pathways intricately links peripheral insulin resistance to brain insulin resistance, in addition to the discovery that insulin receptors are widely expressed in the brain." (PMID 34497507, 2021). "This suggests that HFD PN males developed insulin resistance of the liver, with impaired suppression of hepatic glucose production in response to insulin." (PMID 34977118, 2021). "Curcuminoids have been shown to improve insulin resistance, decrease glucose and insulin levels, increase adiponectin release, and reduce the levels of leptin, resistin, interleukin (IL)-6 IL-1β, and tumor necrosis factor-α in patients with T2DM." (PMID 34012421, 2021). "In insulin resistance, insulin is unable to effectively combine with insulin receptors, and subsequently, the phosphoinositide 3-kinase/protein kinase B signaling is blocked." (PMID 35049893, 2021). "Insulin resistance (IR) is the inability of the insulin hormone to facilitate glucose uptake from peripheral tissues to meet metabolic demands." (PMID 34858210, 2021). "Insulin resistance, defined as a diminished ability to respond to the stimulation of insulin, is the main line for a variety of metabolic-related diseases." (PMID 34262422, 2021). "Insulin resistance is described as a low response to insulin action in adipose tissue, skeletal muscles, and liver." (PMID 34442386, 2021). "In animal models, elimination of NLRP3 inflammasome protects from high-fat induced insulin resistance, while in obese diabetic individuals, adipose tissue expression of NLRP3 inversely correlates with the increase in insulin sensitivity after weight loss." (PMID 34966295, 2021). "Insulin resistance is defined as the failure of anabolic processes to respond to the normal action of insulin and is one of the major metabolic changes in sepsis." (PMID 34072402, 2021). "Insulin resistance is related to the production of beta-amyloid deposits in the CNS, as it is originally hydrolyzed by insulin-degrading enzymes." (PMID 33671898, 2021). "T2DM is a multifactorial heterogenic disease characterized by peripheral insulin resistance or insufficient insulin production by pancreatic β-cells or both, resulting in increased hepatic glucose production." (PMID 34564146, 2021). "Specifically, fasting plasma insulin and glucose contents (except for the Low group) were all reduced after the intervention markedly, accompanied by a lower degree of insulin resistance." (PMID 34595203, 2021). "In these published studies, it has been confirmed that MSC therapy can effectively reduce FBG, PBG, and HbA1c, reduce insulin requirements, and improve insulin resistance in follow-up time, proving that MSC therapy has a significant effect in clinical trials." (PMID 34135959, 2021). "We further calculated the Homeostatic Model Assessment of Insulin Resistance (HOMA-IR) and insulin secretion index as the indicators of insulin resistance and beta cell function." (PMID 33809062, 2021). "A very recent meta-analysis summarises the success of this approach with significant reductions of fasting plasma glucose, insulin, homeostatic model assessment for insulin resistance (HOMA-IR), and glycosylated haemoglobin (HbA1C) concentrations." (PMID 33921022, 2021).